SMARCB1 (SWI/SNF related BAF chromatin remodeling complex subunit B1)
Diseases named in the same sentence as SMARCB1 in open-access papers (continued):
Sharing a sentence is not in itself a finding about the gene and the disease.
cancer (continued). "SMARCB1-deficient cancers are characterized by the biallelic loss of function in both SMARCB1 alleles." (PMID 35892904, 2022). "EZH2 inhibitors have recently made it to the clinic for use in some SMARCB1-deficient cancers and are being explored in a wide range of other cancers." (PMID 35323214, 2022). "indicating that the UPS was a core druggable vulnerability in RMC and other SMARCB1-deficient cancers." (PMID 35806102, 2022). "Clinical benefits of immune checkpoint inhibition in SMARCB1-deficient cancers are currently being studied in several clinical trials." (PMID 35892904, 2022). "Further studies are still needed to confirm if TKIs are a viable therapeutic target for SMARCB1-deficient cancers." (PMID 35892904, 2022). "miR-671 plays a crucial role in the oncogenesis of tumors by silencing SMARCB1 which manifests frequently with a loss-of-function mutation in malignant neoplasms." (PMID 36016604, 2022). "More pre-clinical studies are needed to elucidate the clinical benefit of MDM2/MDM4 inhibition in SMARCB1-deficient cancers." (PMID 35892904, 2022). "Genomic analysis indicates that the residual GBAF activity in SMARCB1-deficient cancers maintains the expression of retained BAF targets." (PMID 35892904, 2022). "This review is focused on one of these BAF subunits, SMARCB1, which has been identified as the sole recurrent genetic alteration present in a variety of cancers known as SMARCB1-deficient cancers." (PMID 35892904, 2022). "Modern advances in diagnostic techniques have identified SMARCB1 loss in numerous other cancers broadly referred to as SMARCB1-deficient cancers." (PMID 35892904, 2022). "Somatic loss of SWI/SNF subunits in cancer, such as SMARCB1 and SMARCA4, lead to the functional dependence on PRC2." (PMID 35169119, 2022). "Loss of SMARCB1 has been identified as the sole mutation in a number of rare pediatric and adult cancers, most of which have a poor prognosis despite intensive therapies including surgery, radiation, and chemotherapy." (PMID 35892904, 2022). "In recent years, there has been a shift toward a more personalized molecular subtyping of each SMARCB1-deficient cancer, such as those four subgroups defined for ATRT." (PMID 35892904, 2022). "Among the six SWI/SNF genes, ARID1A and SMARCB1 were, respectively, the most and least frequently mutated genes in the majority of the cancer types (ARID1A, 10.7%; SMARCA4, 6.0%; ARID1B, 4.7%; ARID2, 4.0%; PBRM1, 3.5%; SMARCB1, 1.3%)." (PMID 36371186, 2022). "EZH2 was found to be upregulated in SMARCB1-deficient cancers, leading to trimethylation of lysine 27 of histone H3 (H3K27); as a result, histone and DNA were tightly bound and polycomb target genes were also broadly repressed." (PMID 35806102, 2022). "Additional new options are on the way, as most recent in vitro data suggest synergistic action of WDR5 and HDM2 inhibitors in SMARCB1-deficient cancer cells." (PMID 35864317, 2022). "More recent reports suggest that SMARCB1-deficient cancers are vulnerable to targeting the ubiquitin-proteasome system (UPS)." (PMID 35806102, 2022). "Further studies are still needed to elucidate the clinical benefits of proteasomal inhibition in SMARCB1-deficient cancers." (PMID 35892904, 2022). "These novel insights have propelled the discovery of numerous potential therapeutic vulnerabilities of SMARCB1-deficient cancers." (PMID 35892904, 2022). "This section outlines the recent advances in the therapeutic targeting of SMARCB1-deficient cancers." (PMID 35892904, 2022). "Only one nasal and sinus YST with SMARCB1-deficient carcinoma (SDC) was reported with follow-up information but the patient died 20 months after diagnosis." (PMID 36514645, 2022). "A recently described tumor of the sinonasal tract, SMARCB1-deficient carcinoma, is characterized by the inactivation of the SMARCB1 (INI1) tumor-suppressor gene." (PMID 36415387, 2022).
cancer (continued). "New tumor entities previously classified as SNUC include SMARCB1-deficient carcinoma, SMARCA4-deficient carcinoma and possibly also IDH2 mutant SNUC." (PMID 36140305, 2022). "Conditional inactivation of Smarcb1 in mice (Smarcb1Flox/Flox, Mx-Cre plus polyI/polyC treatment) results in rapid cancer susceptibility, with all animals developing tumors at a median age of 11 weeks." (PMID 33918045, 2021). "Both RNA interference (RNAi)-mediated BRD9 knockdown and CRISPR-Cas9-mediated BRD9 knockout compromised the proliferation of SMARCB1-mutant MRT cells, providing compelling support that BRD9 is a therapeutic target for SMARCB1-mutated cancers." (PMID 34298819, 2021). "A prime example is BRD9, which is often amplified in cancers but is also a specific vulnerability in SMARCB1-deficient cancers." (PMID 33941852, 2021). "The first example to illustrate this issue are the SMARCB1-deficient cancers that are sensitive to depletion of the ncBAF subunit BRD9." (PMID 33941852, 2021). "Malignant rhabdoid tumors (MRT) are a highly aggressive cancer driven by truncating mutations in the SMARCB1 gene encoding a subunit of the BAF chromatin-remodeling complex." (PMID 34298819, 2021). "Overall, targeting BRD7/9 with conventional BRD inhibitors failed to fully recapitulate the phenotypic response of genetic BRD9 knockout studies in SMARCB1-deficient cancers." (PMID 33941852, 2021). "Cancer-associated mutations of SMARCB1 are found in all domains of the protein, but many mutations affect the C-terminal region." (PMID 34003336, 2021). "We found that the cancer-associated R341L mutation of SMARCB1, also located at the interaction interface of the heterotrimer, affects the interaction between SMARCB1 and SMARCC2 only modestly." (PMID 33024572, 2020). "Our findings demonstrate the efficacious antitumor effects of BTZ in Myc-ATRT cells and orthopedic xenograft Myc-ATRT and strongly support the sensitivity to BTZ in SMARCB1-deficient cancers, particularly the Myc subgroup." (PMID 32235770, 2020). "Patients with RMC and other SMARCB1 deficient cancers have a poor prognosis despite aggressive multi-modal therapy." (PMID 30860482, 2019). "The mutations in SMARCB1 an INI1/SNF5/BAF47-encoding gene were found in this type of cancer, suggesting the mutation in a gene encoding core SNF5-type subunit of SWI/SNF CRCs as a driving mutation for this cancer type." (PMID 31722744, 2019). "On one hand, these cancers have an unusually simple genetic profile, with a single driver mutation—loss of SMARCB1/SNF5—and little if any evidence of collaborating oncogenic events." (PMID 31043611, 2019). "We concluded that the composition of the SWI/SNF complex is similar between RMC and other SMARCB1 deficient cancers." (PMID 30860482, 2019). "Deletion of SMARCB1 serves as a positive control in these SMARCB1 deficient cancers as these cell lines have loss of SMARCB1." (PMID 30860482, 2019). "We reasoned that if our SMARCB1 deficient cancers were susceptible to proteasome inhibitors at similar in vitro dosing, we would also see similar in vivo responses." (PMID 30860482, 2019). "We demonstrate that RMC depends on loss of SMARCB1 for survival and, through integrated genetic and pharmacologic studies, we uncover the proteasome as a core druggable vulnerability in RMC and other SMARCB1-deficient cancers." (PMID 30860482, 2019). "We found that SMARCB1 deficient cancer cell lines required UBE2C, an ubiquitin-conjugating enzyme, for survival." (PMID 30860482, 2019). "An embryonic gene expression signature distinguishes RT from other cancers that are SMARCB1-deficient." (PMID 31123059, 2019). "It has been of additional interest due to the remarkably unaltered genomes found in SMARCB1-mutant cancers demonstrating potent cancer driving activity caused by SMARCB1 loss." (PMID 31015438, 2019).
cancer (continued). "Our findings suggest that testing oral proteasome inhibitors such as MLN2238 for patients with RMC and potentially more broadly across SMARCB1-deficient cancers is warranted." (PMID 30860482, 2019). "BRD9 is essential for the proliferation of SMARCB1-deficient cancer cell lines, suggesting it as a therapeutic target for these lethal cancers." (PMID 31015438, 2019). "When we looked more broadly at other SMARCB1 deficient cancers such as MRT and ATRT, we found that these models were similarly sensitive to inhibition of the ubiquitin-proteasome system." (PMID 30860482, 2019). "In sum, these observations indicate that the RMC cell lines are functionally similar to those derived from other SMARCB1 deficient cancers." (PMID 30860482, 2019). "This dataset included loss of function screens from 485 cancer cell lines and included three ATRT SMARCB1-deficient cancer cell lines: COGAR359, CHLA06ATRT and CHLA266." (PMID 30860482, 2019). "We found that proteasome inhibition in SMARCB1-deficient cancer cell lines results in G2/M arrest due to inappropriate degradation of cyclin B1." (PMID 30860482, 2019). "(d) Analysis of differentially expressed genes when SMARCB1 was re-expressed in SMARCB1 deficient cancers compared with differentially expressed genes when SMARCB1 deficient cancers were treated with 200 nM MLN2238." (PMID 30860482, 2019). "Since activation of c-MYC has been observed in SMARCB1-deficient cancers, we assessed how c-MYC levels are altered upon proteasome inhibition." (PMID 30860482, 2019). "We then compared the results of small-molecule screens performed in SMARCB1-deficient cancer cell lines in CCLE to the rest of the CCLE cell lines (n = 835)." (PMID 30860482, 2019). "Proteasome inhibitors such as MLN2238 are specific to SMARCB1 deficient cancers and lead to cell cycle arrest and programmed cell death." (PMID 30860482, 2019). "Nonetheless, these mouse experiments established that loss of Smarcb1 causes cancer in mouse models." (PMID 31123059, 2019). "Re-expression of SMARCB1 leads to significant decreases in cell viability as compared to LacZ control in SMARCB1 deficient cancer cell lines G401, CLF_PEDS9001_T, and CLF_PEDS0005." (PMID 30860482, 2019). "Reversible conditional inactivation of Smarcb1 in mice revealed that, while it is essential for the survival of most normal cells, it also causes highly penetrant and aggressive cancers." (PMID 31123059, 2019). "SMARCB1 deficiency is used to define malignant rhabdoid tumors (MRTs) and some carcinomas with rhabdoid features." (PMID 30649642, 2019). "Recently, SMARCB1-deficient carcinomas arising from some visceral organs including sinonasal tract, gastrointestinal tract and pancreas have been reported." (PMID 29625594, 2018). "In order to compare these features with other late-onset SMARCB1-deficient cancers, we assessed the genomic landscape of 8 SD-NRT from the study cohort, 7 by exome sequencing, and one by array-CGH." (PMID 28427232, 2017). "An imbalance in their activities induced by mutations/deletions in complex members (e.g. SMARCB1) has been suggested to be a pathogenic mechanism in certain human cancers." (PMID 27391784, 2016). "As more and more tumors are deep sequenced, mutations in SMARCB1 are found across a growing spectrum of cancers." (PMID 26370283, 2015). "Among the nine selected cancer associated genes with germline variants SMARCB1 was downregulated and so was CNTN6, whereas MYCL was upregulated." (PMID 26998479, 2015). "Three of the five tumors had a T2/OncZ insertion in one gene (CBL, TSHR, or SMARCB1) known to be highly mutated in human cancers." (PMID 21533036, 2011). "Another setting in which compensatory mechanisms within BAF‐complexes lead to synthetic lethality that can be leveraged for targeted cancer therapies is cancers with SMARCB1 mutations, found in a variety of mesenchymal neoplasms including rhabdoid tumors and other sarcomas." (PMID 40181550, 2026).
cancer (continued). "Given the discordance of our in vitro studies on the recurrent R377H mutation and the fact that these computational tools predict pathogenic effects broadly outside a cancer-specific context, we sought to investigate the functional effects of all possible missense mutations in SMARCB1 using DMS." (PMID 40196006, 2025). "Modern diagnostic technology has identified a type of cancer called SMARCB1-deficient cancer." (PMID 40115023, 2025). "Such an approach may be especially useful for rarer cancers such as SMARCB1-deficient rhabdoid malignancies, which tend to have a relatively limited specific research focus." (PMID 40422882, 2025). "Though high methylation entropy has been reported as a mechanism of transcriptional plasticity in cancer and development, further studies are also necessary to elucidate the link between altered epigenetic drivers such as SMARCB1 loss and downstream changes in methylation entropy." (PMID 41408661, 2025). "Previously, we found that histone acetyltransferases CBP/p300 dual inhibitors could be promising treatments for SMARCB1-deficient cancers." (PMID 39625239, 2025). "Taken together, our findings indicate that simultaneous inhibitors of CBP/p300 could be promising therapeutic agents for SMARCB1-deficient cancers." (PMID 38839769, 2024). "In addition, expression levels of KREMEN2 pre-mRNA in SMARCB1-deficient cell lines was higher than that in SMARCB1-proficient cell lines in the cancer cell line model." (PMID 38839769, 2024). "Therefore, in this study, we focused on the paralog pair CREBBP and EP300 as a synthetic lethal target for SMARCB1-deficient cancers." (PMID 38839769, 2024). "In this study, we searched for a promising synthetic lethal target for SMARCB1-deficient cancers among chromatin regulators; this is because SMARCB1 is involved in chromatin regulation and there are cases in which functionally related chromatin regulators show synthetically lethal properties." (PMID 38839769, 2024). "Here, we aim to identify paralog pairs as a synthetic lethal target for SMARCB1-deficient cancers." (PMID 38839769, 2024). "Immune checkpoint blockade is another area that is being trialed in SMARCB1-deficient cancers." (PMID 39125735, 2024). "SMARCB1 inactivation led to large-scale loss of kidney-specific epigenetic programs and restoration of proliferative capacity through the adoption of new dependencies on factors that represent rare essential genes across different cancers." (PMID 37554444, 2023). "Cancers harboring serine threonine kinase (STK11) alteration or SWI/SNF-related, matrix-associated, actin-dependent regulator of chromatin, subfamily B, member 1 (SMARCB1) mutation are conventionally considered as treatment-refractory to immune checkpoint inhibitors or chemotherapy, respectively." (PMID 36776287, 2023). "Loss of SMARCB1 is characteristic of malignant tumors with rhabdoid features." (PMID 36732357, 2023). "By contrast, SMARCB1 only reported three LoF variants in the non‐cancer gnomAD cohort (Ensembl canonical transcript ENST00000263121.7, Accessed February 3, 2022), which means that there were 3 from a mean of 118,374 individuals (1 in 39,458) with an LoF variant." (PMID 35391499, 2022). "But most tumors are accompanied by SMARCB1 deficiency, which may offer new research directions for cancer therapeutics." (PMID 35062870, 2022). "As pointed in the adenocarcinoma section, a subset of SMARCB1 deficient carcinomas presents a predominant oncocytoid/plasmacytoid cytology together with true glandular differentiation consisting of the formation of cribriform structures and tubules with intracellular and/or intraluminal mucin." (PMID 35326613, 2022). "SMARCB1-deficient carcinomas have also been described among SNEC." (PMID 36431263, 2022). "The histologic and immunophenotypic features of SMARCB1 deficient carcinoma are heterogenous." (PMID 35326613, 2022).
cancer (continued). "In addition, SMARCB1 deficient carcinomas are consistently positive for cytokeratins, including variable positivity for CK5 and CK7, while p63 is expressed in approximately half of the cases." (PMID 35326613, 2022). "A definitive cancer risk cannot be extrapolated for patients with distal 22q11.2 deletion syndrome, but deletions encompassing SMARCB1 should receive vigilant surveillance from birth to adulthood as large deletions may predispose to late occurrence of MRT." (PMID 33532948, 2021). "Strikingly, these included five cases (EIF1AX, HIST1H3B, MLH1, RPS15, SMARCB1) where not only the gene/protein, but also the region primarily mutated in human cancers were very ancient and could be traced back to unicellular organisms." (PMID 32731489, 2020). "A frameshift mutation in SMARCB1 is commonly observed in pan-cancer analysis." (PMID 32235312, 2020). "Moreover, the correlation of Myc activity and SMARCB1-deficient cancers has been identified in priors studies." (PMID 32235770, 2020). "Patient-derived models of RMC are functionally similar to SMARCB1 deficient cancers." (PMID 30860482, 2019). "To assess whether RMC cells exhibit an increased proclivity to undergo cell death after cell cycle arrest, we asked whether treatment of SMARCB1-deficient cancers with cell cycle inhibitors led only to cell cycle arrest or arrest followed by cell death." (PMID 30860482, 2019). "These proteasome inhibitor drugs also killed other kinds of cancer cells with SMARCB1 mutations." (PMID 30860482, 2019). "However, the expansion of the SMARCB1-deficient family of cancers and the pleomorphic morphology of RT has definitely challenged this simplistic definition." (PMID 28427232, 2017). "The main clinical perspective of our work is to find some biological features that may help pathologists to classify SMARCB1-deficient cancers in the appropriate entity." (PMID 28427232, 2017). "Altogether, our study helps defining RT among a wide series of SMARCB1-deficient cancers." (PMID 28427232, 2017). "SMARCB1 (INI1 or BAF47) was the first gene of the SWI/SNF complex that was linked to cancer." (PMID 25774356, 2014). "The cancer-associated ATP-dependent chromatin remodeling enzymes SMARCB1 (SWI/SNF-related, matrix-associated, actin-dependent regulator of chromatin, subfamily B, member 1) and BRG1 (brahma-related gene 1), and BRM (brahma) regulate gene expression by altering nucleosome spacing." (PMID 19721813, 2009). "Indeed, we identified promising simultaneous inhibitors of CBP/p300 in SMARCB1-deficient cancers." (PMID 39625239, 2025). "Furthermore, we proposed the following molecular mechanism underlying synthetic lethality induced by simultaneous inhibition of CBP/p300 in SMARCB1-deficient cancers: in SMARCB1-proficient cells, the SWI/SNF complex containing SMARCB1 represses transcription of KREMEN2." (PMID 39625239, 2025). "Thus, this study is the first to show that SMARCB1-deficient tumors resist EGFR-TKIs in cancer." (PMID 39971779, 2025). "Thus, SMARCB1-deficient cancer cells are dependent on KREMEN2 expression." (PMID 38839769, 2024). "In the present study, we found that the CBP/p300 dual inhibitor CP-C27 showed higher selectivity and potency than tazemetostat in SMARCB1-deficient cells, indicating that CBP/p300 dual inhibitors such as CP-C27 may be promising treatments for SMARCB1-deficient cancers." (PMID 38839769, 2024). "Simultaneous inhibitors of CBP/p300 could be therapeutic agents for SMARCB1-deficient cancers." (PMID 38839769, 2024). "Interestingly, yolk sac tumor elements have been observed in SMARCB1 deficient carcinomas and adenocarcinomas and could represent a morphologic link between different entities in the spectrum of SWI/SNF complex deficient malignancies of the sinonasal tract." (PMID 35326613, 2022).